GDF15 (growth differentiation factor 15)
Diseases named in the same sentence as GDF15 in open-access papers (continued):
Sharing a sentence is not in itself a finding about the gene and the disease.
glioblastoma (continued). "Although requiring confirmation in another dataset with control for other prognostic factors, these findings corroborate previous reports indicating that GDF-15 contributes to the malignant phenotype of glioblastoma." (PMID 26741507, 2016). "When the median was used as cut-off, glioblastoma patients with tumors displaying lower GDF-15 expression had longer overall survival than patients with tumors characterized by GDF-15 expression higher than the median (p = 0.017)." (PMID 26741507, 2016). "To assess the overall prognostic role of GDF-15 in glioblastoma, we performed a TCGA database interrogation." (PMID 26741507, 2016). "Increased GDF-15 levels have been found in the blood of glioblastoma patients and in the CSF where it correlates with poor patient outcome." (PMID 26741507, 2016). "To elucidate the role of GDF-15 in glioblastoma in detail, we confirmed that glioma cells express GDF-15 mRNA and protein in vitro." (PMID 26741507, 2016). "We and others have previously reported that GDF-15 levels are elevated in the blood and cerebrospinal fluid of glioblastoma patients." (PMID 26741507, 2016). "By contrast, knock down of MIC-1/GDF15 in a human melanoma and a mouse glioblastoma cell line significantly decreased the growth of engrafted tumors." (PMID 25695521, 2015). "The results from this study suggest that targeting the GDF15/PD-L1 pathway could be an effective immunotherapy strategy to enhance anti-tumor immunity in glioblastoma." (PMID 36353620, 2022). "In this study, we hypothesized that irradiation-induced GDF15 promotes angiogenesis in glioblastoma by functioning as a cytokine in the tumor microenvironment." (PMID 35280749, 2022). "Thus, it represents a potential therapeutic target in glioblastoma treatment by siRNA targeting GDF15 or its cognate receptor GFRAL (the GDNF family receptor alpha like)." (PMID 34532286, 2021). "The expression of GDF-15 in secondary glioblastomas is much higher than in primary glioblastomas." (PMID 29467963, 2018). "GDF-15 levels are increased in the blood and cerebrospinal fluid of glioblastoma patients." (PMID 26741507, 2016). "Moreover, the four glioblastoma subtypes defined by Verhaak and colleagues exhibited different GDF-15 expression patterns, with lowest levels in the proneural subtype." (PMID 26741507, 2016). "In light of the various immunotherapeutic approaches which are currently being investigated in glioblastoma patients, the autocrine and paracrine functions of GDF-15 may make it an attractive target for novel therapeutic strategies." (PMID 26741507, 2016). "Similarly, previous studies have shown that GDF15 may promote proliferation in glioblastoma cells, support tumour growth by stimulating angiogenesis, and be associated with adverse prognostic outcomes when highly expressed." (PMID 41009755, 2025). "Glioblastomas induce them to adopt an activated phenotype; in cell culture, co-culture of glioblastoma cells with macrophages or microglia induces the latter to adopt an M2-like immunosuppressive phenotype, a process that is mediated by various cytokines including CSF-1, TGFβ, and GDF15." (PMID 33753869, 2022). "Therefore, GDF15 is a potential therapeutic target for glioblastoma." (PMID 35280749, 2022). "Within this cluster analysis, the overall survival probability was significantly higher for patients of group G4, which is characterized by the lowest GDF-15 levels, corroborating the hypothesis that GDF-15 contributes to the malignant phenotype of glioblastoma." (PMID 26741507, 2016). "In glioblastoma (GBM), high GDF15 expression correlates with reduced tumor-infiltrating lymphocytes." (PMID 40868185, 2025).
glioblastoma (continued). "GDF15, a member of the TGF-β family of proteins, known to be involved in actin cytoskeleton reorganization, is elevated in glioblastoma patients’ serum." (PMID 31412547, 2019). "It has been shown that inhibition of STAT3 in glioblastoma stem cells (GBM-SC) can promote the levels of histone H3K27 demethylation and the expression of neural-specific genes, such as FGF21, GDF15, and Myt1." (PMID 34217316, 2021). "A tumorigenic glioblastoma cell line, that remained unaffected by MIC-1/GDF15 in vitro, on transfection with MIC-1/GDF15, failed to develop tumors in nude mice." (PMID 25695521, 2015). "Additionally, GDF-15 is a novel regulator of PD-L1 expression in glioblastoma multiforme (GBM); thus, targeting the GDF15/PD-L1 pathway might be a promising treatment for GBM patients." (PMID 36230513, 2022). "Interestingly, although STAT3 inhibition induces neural genes, such as FGF21 and GDF15, neither Jmjd3 overexpression or STAT3 inhibition are sufficient to drive differentiation of the glioblastoma stem cells." (PMID 28384648, 2017). "High expression level of GDF15 predicted poor survival in LGG, while the effect on glioblastoma (GBM) was not significant." (PMID 34697897, 2022).
acute kidney injury (39 papers, 2014 to 2026). Sudden and sustained deterioration of the kidney function characterized by decreased glomerular filtration rate, increased serum creatinine or oliguria. "Assessing GDF-15 together with creatine kinase provides a more robust approach for early identification of acute kidney injury risk in patients suffering from trauma- or exercise-related rhabdomyolysis." (PMID 40731746, 2025). "Gdf15-deficient mice developed more severe toxic acute kidney injury, while GDF15 overexpression or GDF15 administration was protective." (PMID 40565178, 2025). "Acute kidney injury has recently been associated with increased levels of baseline serum GDF-15 after coronary artery bypass surgery and cardiac surgery in general." (PMID 34441356, 2021). "This study evaluated the association between GDF-15 and in-hospital mortality among patients with severe acute kidney injury (AKI) requiring continuous renal replacement therapy (CRRT)." (PMID 34441955, 2021). "Circulating GDF‐15 levels are associated with oxidative stress marked by 8‐oxo‐dG in patients with renal failure." (PMID 27239406, 2016). "An increase in GDF-15 has been reported in association with faster deterioration in kidney function in patients with type 1 diabetes, as well as after acute kidney injury." (PMID 27043030, 2016). "Patients with CAD undergoing bypass surgery are at increased risk to develop acute kidney injury when their pre-operative GDF-15 levels were elevated." (PMID 27056183, 2016). "Moreover, the overexpression of GDF15 or its administration resulted in less severe acute kidney injury than that seen in GDF15-deficient mice in response to treatment with cisplatin or folic acid." (PMID 38132468, 2023). "Similarly, GDF-15 has proven successful in the identification of patients at increased risk for acute kidney injury after cardiac surgery." (PMID 35054405, 2021). "Furthermore, our findings are in agreement with reports indicating the association of elevated circulating levels of GDF15 with stress conditions such as myocardial injury or acute kidney injury." (PMID 32671100, 2020). "GDF15 has been reported to be predictive in patients with acute kidney injury (AKI) and is particularly helpful for risk stratification in AKI patients with normal levels of creatinine." (PMID 40673270, 2025). "Among all the post-operative biomarkers available, only eGFR, NGAL and GDF-15 measured at ICU arrival were significantly associated with the onset of acute kidney injury (AKI)." (PMID 25171167, 2014). "In transcriptomic analyses of experimental acute kidney injury and renal fibrosis, GDF15 was the most significantly upregulated gene in the GDF family." (PMID 41602837, 2026). "Over-expression of GDF15 protects renal function and prevents renal failure, highlighting its potential in treating renal failure." (PMID 40673270, 2025). "Materials and Methods: A novel scoring system, termed the growth differentiation factor-15-trauma-creatine kinase acute kidney injury score (GDF-TRACK-AKI score), was established." (PMID 40731746, 2025). "When prognostic parameters were compared for predicting hospital mortality in acute kidney injury patients, GDF-15 was the most sensitive and specific when compared independently by integrating with other parameters." (PMID 39781722, 2025). "In acute kidney injury, GDF-15 levels rise quickly and have been shown to protect renal tubular cells against cytotoxic damage." (PMID 40722837, 2025). "In different disease models, only one study investigated the correlation between GDF-15 and Klotho protein in acute kidney injury and kidney fibrosis and found that GDF-15 and Klotho protein levels have a strong correlation." (PMID 38672115, 2024). "On the other hand, to the best of our knowledge, this is the first study that associates both pericardial fluid and serum GDF-15 and NT-pro-BNP in AVR surgery with AF, as well as acute kidney injury." (PMID 34441356, 2021).
acute kidney injury (continued). "Renal expression of Gdf15 mRNA is increased in a mouse ischemia reperfusion model of acute kidney injury." (PMID 32310257, 2020). "In the previous study, the incidence of postoperative acute kidney injury increased in patients with high level of preoperative plasma GDF-15, indicating that GDF-15 is useful for risk stratification of CIN in patients with normal creatinine." (PMID 29791474, 2018). "GDF-15 has an important role in predicting mortality in acute kidney injury." (PMID 39781722, 2025). "Importantly, the association of GDF15 with the development of CKD and acute kidney injury in these studies persists after adjustment for important covariates, including age and smoking." (PMID 32310257, 2020). "The present secondary analysis of an observational cohort study aimed to determine the role of GDF-15 in predicting CSA-AKI compared with the Cleveland-Clinic Acute Renal Failure (CC-ARF) score and a logistic regression model including variables associated with renal dysfunction." (PMID 27717384, 2016). "GDF15 seems also to be involved in the pathological processes following acute kidney injury (AKI), since its expression is triggered early in PST S3 and principal cells (PC) of CD." (PMID 38892145, 2024). "In physiological conditions, expression of serum GDF-15 is modest, whereas it is elevated in pathological conditions, such as in patients with renal failure, chronic liver disease, and rheumatoid arthritis (RA), suggesting that GDF-15 may be a potential biomarker for diseases." (PMID 35911685, 2022). "We investigated the relationships between preoperative serum GDF-15, ET-1 levels, and intraoperative factors and short-term operative risks including acute kidney injury (AKI) for patients undergoing cardiovascular surgery." (PMID 34063283, 2021). "In addition, GDF15 can also increase in response to acute kidney injuries." (PMID 32375259, 2020). "The postoperative GDF-15 value has also been reported to reflect post-operative acute kidney injury (AKI) in CABG patients." (PMID 31581569, 2019). "For example, administration of GDF15 increased klotho expression and reduced FGF23 levels in an experimental model of acute kidney injury (AKI) through folic acid." (PMID 40563333, 2025). "Notably, patients who developed postoperative acute kidney injury (AKI) or required prolonged hemodynamic support had significantly higher GDF15 levels, with increased mechanical ventilation time and extended intensive care unit length of stay." (PMID 39766300, 2024). "Rates of renal replacement therapy in the context with acute kidney failure were not increased with raised GDF-15 levels." (PMID 34221186, 2021). "In the context of acute kidney injury, the TGF-ß family member GDF15 is rapidly upregulated." (PMID 32375259, 2020).
melanoma (39 papers, 2008 to 2026). A malignant, usually aggressive tumor composed of atypical, neoplastic melanocytes. "Autocrine production of GDF-15 has also been implicated in tumor vascularization during melanoma development in an in vivo mouse model." (PMID 41596411, 2026). "It was reported that GDF15 was overexpressed in melanoma cells and was associated with depth of tumor invasion and metastasis 4, which is in line with our findings." (PMID 38230211, 2024). "Mechanistically, BET inhibitors sensitized melanoma cells to sunitinib by inhibiting the expression of growth differentiation factor 15 (GDF15), a protein associated with tumor progression and resistance to therapy." (PMID 38791873, 2024). "Growth differentiation factor 15 (GDF15) has been shown to be upregulated in melanoma and is associated with poor prognosis." (PMID 38230211, 2024). "It is known that GDF15 overexpression in melanoma cells is associated with tumor invasion and metastasis." (PMID 34552568, 2021). "Additionally, the up-regulation of GDF15 has also been associated with advanced melanoma tumor invasion and metastasis, contradicting our findings." (PMID 40699755, 2025). "Firstly, what causes overexpression of GDF15 in melanoma cells remain unclear." (PMID 38230211, 2024). "This study identifies Growth Differentiation Factor-15 (GDF-15) as a novel mechanosensing-regulated driver of melanoma pathogenesis across melanoma types." (PMID 41648434, 2026). "Consistently, the circulating level of GDF-15 in the blood of melanoma patients has been proposed to predict anti-PD-1 therapy outcome." (PMID 41596411, 2026). "As a result, GDF15 has been shown to have undetectable tissue levels in normal melanocytes, whereas more than half of melanoma cells express it at high concentrations." (PMID 40868185, 2025). "In melanoma, it has been demonstrated that tissue GDF15 overexpression is probably a product of the V600EB-Raf mutation in vitro and it influences melanocyte differentiation, proliferation, and angiogenetic processes." (PMID 40868185, 2025). "Supporting this observation, patients with low plasmatic levels of GDF-15 show better response rates to anti-PD-1/PD-L1 inhibitors in advanced non-small cell lung cancer and in melanoma." (PMID 39000420, 2024). "We firstly demonstrated the regulatory role of GDF15 in malignant melanoma through targeting PTEN/PI3K/AKT pathway in both invitro and vivo levels." (PMID 38230211, 2024). "Several studies have demonstrated that GDF15 is involved in the regulation of cell proliferation, migration, and invasion in melanoma cells." (PMID 38230211, 2024). "Mechanistically, BET inhibitors sensitize melanoma cells to sunitinib by inhibiting the BRD4/GDF15 axis and BRD4/IL6/STAT3/GDF15 axis." (PMID 36720918, 2023). "Altogether, these findings suggest that BET inhibitor-mediated GDF15 inhibition plays a critical role in enhancing sunitinib sensitivity in melanoma, indicating that BET inhibitors synergize with sunitinib in melanoma." (PMID 36720918, 2023). "GDF-15 blockade thus enables human effector T cells to infiltrate patient-derived melanomas in humanized mice." (PMID 37474523, 2023). "Clinically even more striking is the strong correlation between high levels of GDF-15, failure of anti-PD-1 monotherapy and poor survival in two independent cohorts of melanoma patients." (PMID 37474523, 2023). "In melanoma patients, GDF-15 serum levels strongly correlate with failure of PD-1-based immune checkpoint blockade therapy." (PMID 37474523, 2023). "Based on the identified peak, we designed primers for ChIP‐qPCR analysis, confirming that STAT3 binds to the GDF15 promoter in melanoma cells." (PMID 36720918, 2023). "As expected, increased expression of GDF15 in B16F1 melanoma cells promoted tumor growth in the B16F1 melanoma mouse model." (PMID 36720918, 2023).
melanoma (continued). "We further showed that BET inhibitors sensitize melanoma cells to sunitinib by repressing GDF15 expression in a direct way by targeting its promoter or indirectly by targeting the IL6/STAT3 axis." (PMID 36720918, 2023). "Brain metastases from human melanoma are well-suited to assess correlations between GDF-15 and T cell infiltration, as these lesions are typically only resected once they have grown to a size that allows for a proper histopathological assessment." (PMID 37474523, 2023). "Nevertheless, among melanoma patients responding to ipilimumab, only those with low GDF-15 levels showed durable responses and survival >1 year." (PMID 37474523, 2023). "GDF15 expression was found to be increased in melanoma metastases compared with benign nevi or primary melanomas and was positively correlated with stage in melanoma patients." (PMID 36720918, 2023). "Mechanistically, BET inhibitors sensitize melanoma cells to sunitinib by inhibiting GDF15 expression." (PMID 36720918, 2023). "Most importantly, clinical data from two independent melanoma patient cohorts indicate that elevated GDF-15 serum levels correlate with resistance to PD-1-based immune checkpoint blockade." (PMID 37474523, 2023). "Previous studies have shown that hsa-miR-873-5p inhibits the translation of endogenous growth differentiation factor 15 (GDF15) in melanoma cell lines." (PMID 35300113, 2022). "Raised levels of GDF-15 are also measured in kidney failure and various types of cancer such as colon, prostate, or melanoma." (PMID 34221186, 2021). "GDF15 was also reported to be highly expressed in multiple myeloma, malignant melanoma, ovarian cancer and gastric cancer." (PMID 34681812, 2021). "In this study, we discovered that both hsa-miR-873-5p and hsa-miR-1233-3p repressed endogenous GDF15 translation in a melanoma cell line, indicating that the GDF15 transcript is indeed a target of these miRNAs." (PMID 28806401, 2017). "To determine the effect of hsa-miR-873-5p and hsa-miR-1233-3p on endogenous GDF15 protein expression, we transfected the two mimic miRNAs into the A2058 melanoma cell line." (PMID 28806401, 2017). "High MIC-1/GDF15 serum levels also predict diagnosis and/or outcome for a wide range of malignancies including melanoma, cancers of the pancreas, thyroid, ovary and endometrium." (PMID 25695521, 2015). "In this study, ECM rigidity was recapitulated using cell-adhesive gelatin methacryloyl (GelMA) hydrogel microparticles (microgels) with tunable stiffness, providing a biomimetic platform to investigate how mechanical cues in the tumor microenvironment regulate GDF-15 expression in melanoma." (PMID 41648434, 2026). "Notably, GDF-15, also known as macrophage inhibitory cytokine-1, is overexpressed in melanoma cells in vitro compared to normal human melanocytes, and higher levels of this factor in vivo are associated with metastatic disease." (PMID 41596411, 2026). "We speculate that GDF15 might regulate the development of melanoma through affecting PTEN/PI3K/AKT signaling pathway." (PMID 38230211, 2024). "Furthermore, elevated GDF15 levels were detected in melanoma tissues and specific cell lines (UACC62, M14, A375, and M21) as compared to normal skin tissues and the HEM cell line, with samples sourced from our hospital." (PMID 38230211, 2024). "Significant higher expression of GDF15 in melanoma was observed." (PMID 38230211, 2024). "This study might provide a new understanding for the regulatory role of GDF15 in malignant melanoma." (PMID 38230211, 2024). "A significantly higher GDF15 expression was observed in melanoma patients compared to controls." (PMID 38230211, 2024). "To further elucidate the regulatory mechanism of GDF15 in melanoma cells, we first measured the expression of GDF15 in STAT3-silenced cells and found that the expression of GDF15 in STAT3-silenced cells was significantly reduced compared with that in control cells." (PMID 36720918, 2023).